ACLY (ATP citrate lyase)
Diseases named in the same sentence as ACLY in open-access papers (continued):
Sharing a sentence is not in itself a finding about the gene and the disease.
lung cancer (44 papers, 2012 to 2025). A malignant neoplasm involving the lung. "In human lung cancer patients, overexpression of ACLY and FASN in tumor tissues are observed and associated with a poor post-treatment survival rate." (PMID 38069382, 2023). "In osteosarcoma, prostate, cervical, and lung cancers, miR‐22 was reported to directly downregulate ACLY through posttranscriptional effects and was associated with tumor growth and metastasis." (PMID 34766135, 2021). "High expression of SLC25A1 or ACLY has been reported in multiple cancers including colorectal, breast, and lung cancer." (PMID 39881208, 2025). "Another important enzyme in lung cancer is ATP-citrate lyase (ACLY), a key enzyme of de novo fatty acid synthesis which is responsible for the transformation of TCA-derived citrate into acetyl-CoA." (PMID 38731909, 2024). "ACLY is closely related to local tumour stage and overall survival in patients with non‐small‐cell lung cancer, and lung cancer patients with high ACLY expression have a poorer overall survival rate." (PMID 38426936, 2024). "On the contrary, ACLY, as a potential risk gene for prognosis, is overexpressed in various cancers such as HCC, lung cancer, bladder cancer, prostate cancer, colorectal cancer, and gastric cancer." (PMID 38282028, 2024). "Remarkably, the acetylation of ACLY results in its accumulation and enhanced fatty acid synthesis, thereby promoting tumor growth in lung carcinoma." (PMID 39551780, 2024). "In lung cancer cells, ACLY is specifically targeted for degradation by the Cullin3–KLHL25 ubiquitin ligase system." (PMID 39551780, 2024). "Previous studies have proved that the expressions of ACLY were increased in colorectal cancer, bladder cancer, lung cancer, glioblastoma, etc., and promoted tumor growth." (PMID 36241648, 2022). "ACLY is reportedly overexpressed in many types of cancers, including osteosarcoma, cervical cancer, prostate cancer, lung cancer, hepatic, and colorectal cancers, and can contribute to tumour progression." (PMID 36064336, 2022). "ACLY and FASN upregulation has been shown in colorectal, gastric, breast, liver, and lung cancer, and their overexpression has been significantly associated with poor survival in lung cancer patients." (PMID 35159223, 2022). "Many enzymes in the fatty acid biosynthesis were found upregulated in many lung cancer cells, including the rate-limiting enzymes, ATP citrate lyase (ACLY), acetyl-CoA carboxylase (ACC), fatty acid-synthase (FASN), and phosphatidic acid phosphatase (Lipin1)." (PMID 36293388, 2022). "Mutant KRas upregulates de novo lipogenic genes, including FASN, ACC1, and ACLY, in lung cancer and gemcitabine-resistant pancreatic cancer cells, implying that KRAS-mutant cancer cells are more sensitive to inhibitors of FA synthesis." (PMID 33801246, 2021). "Endogenous H2S promotes cancer cell migration and invasion in multiple cancer types, such as prostate cancer, lung cancer, colon cancer, and liver cancer, partly through induction of ATP citrate lyase (ACLY) to facilitate EMT." (PMID 34207284, 2021). "The ACLY inhibitor SB‐204990 has been shown to inhibit the proliferation of lung cancer cells in vivo and in vitro." (PMID 34766135, 2021). "A Kelch-like family member, KLHL25, bound cul3 to ubiquitinate and degrade ACLY, thereby inhibit inhibits tumor progression of lung cancer cells." (PMID 33109073, 2020). "ACLY is overexpressed in cancer cells, and siRNA-mediated silencing of ACLY limits cancer cell proliferation and reduces the capacity of A549 lung cancer cells to form spheres." (PMID 32028963, 2020). "Phosphorylated ACLY expression levels are a significant factor for predicting a poor prognosis in non–small cell lung cancer, together with clinical stage and tumor size." (PMID 31511060, 2019). "In an in vitro lung cancer cell model, knockdown of ACLY inhibits epithelial–mesenchymal transition (EMT), a phenomenon often linked to cancer stemness, and results in a decrease of tumorsphere formation." (PMID 29996946, 2018).
lung cancer (continued). "Phosphorylation at ACLY serine 454 by AKT is increased in lung cancer and is correlated with enhanced activity of ACLY." (PMID 29996946, 2018). "In our work, we documented the direct downregulation relationship between miR-22 and ACLY in cancers such as osteosarcoma, prostate, cervical and lung cancers." (PMID 27317765, 2016). "It was reported that miR-22 inhibits tumor metastasis by directly targeting ATP citrate lyase in osteosarcoma, prostate cancer, cervical cancer and lung cancer." (PMID 27811373, 2016). "Herein, four different types of tumor cells including osteosarcoma, prostate, cervical and lung cancers were adopted in our study, and we have demonstrated that miR-22 directly downregulated ACLY." (PMID 27317765, 2016). "For the further verification of the relationship between ACLY and miR-22 in osteosarcoma, prostate, cervical and lung cancers, immunohistochemistry (IHC) staining and a RISH method were performed on human tissue microarrays." (PMID 27317765, 2016). "Knockdown of ATP citrate lyase was shown to reverse EMT in lung cancer cells, while knockdown of citrate synthase was found to induce EMT." (PMID 25502225, 2014). "Acetylation of ACLY at Lys‐540, Lys‐546 and Lys‐554 (ACLY‐3 K) can antagonize ubiquitination of ACLY, leading to increased stability of ACLY protein, and further promoting lipid synthesis and cell proliferation of lung cancer cells." (PMID 38426936, 2024). "ATP citrate lyase and FASN upregulation has been shown in colorectal, gastric, liver, and lung cancer, and their overexpression has been significantly associated with poor survival in lung cancer patients." (PMID 38874588, 2024). "ACLY expression and activity proved to be aberrantly expressed in liver cancer, colorectal cancer, lung cancer, prostate cancer, bladder cancer, stomach cancer and other cancers, and its pharmacological or genetic inhibition significantly inhibited cancer cell proliferation and induced apoptosis." (PMID 37601252, 2023). "In addition, glucose injection induces acetylation of lysine residues of ACLY in lung cancer A549 cells and mouse liver, blocking ubiquitination and increasing ACLY protein expression." (PMID 38060103, 2023). "SB-204990 was found to abolish the promoting effect of Cullin3 downregulation on lipid synthesis, cell proliferation, and tumor growth, suggesting that targeting ACLY could be a potential therapeutic strategy for lung cancer with reduced expression of Cullin3." (PMID 35159223, 2022). "Moreover, inhibition of ACLY, either pharmacologically or through RNAi, resulted in cell cycle arrest and apoptosis induction in lung cancer cells in vitro and in vivo as its inhibition led to depleted levels of AcCoA, which resulted in FA synthesis reduction." (PMID 35159223, 2022). "Furthermore, miR-22 is known to inhibit ATP citrate lyase (ACLY) in osteosarcoma and cervical, prostate, and lung cancer cells." (PMID 36013278, 2022). "Conversely, the down-regulation of ACLY by miR-22 was shown to attenuate cancer cell proliferation and invasion, as well as promote cell apoptosis in different types of tumor cells including osteosarcoma, prostate, cervical, and lung cancers." (PMID 34573442, 2021). "As we have stated, dichloroacetate, which inhibits PDK1 and restores drug sensitivity in paclitaxel-resistant lung cancer cells (A549), increases cytosolic citrate, while ACLY inhibition, which reduces tumor growth in various models, likely increases citrate level." (PMID 34205414, 2021). "Thus our data suggests that dysregulation of caspase-10 expression and consequent upregulation of ACLY is critical for lung cancer progression." (PMID 31534141, 2019). "Most importantly, the acetylation levels of ACLY are elevated in lung cancers, implying that ACLY acetylation could be a potential biomarker for lung cancer diagnosis." (PMID 30283496, 2018).
lung cancer (continued). "In addition, miR-22 also suppresses cancer metastasis by targeting ATP citrate lyase in osteosarcoma, prostate cancer, cervical cancer and lung cancer." (PMID 27811373, 2016). "In this study, we investigated the four representative tumors, including osteosarcoma, prostate, cervical and lung cancers, and uncovered that ACLY is directly downregulated by miR-22, which has implications for the potential therapeutic disruption of tumor development and progression." (PMID 27317765, 2016). "For instance, activated enzymes like ACLY, ACC, FASN, and SCD1 were highly expressed in lung cancer tissues, which are correlated with a worse prognosis among patients having NSCLC." (PMID 39323079, 2024). "Their research results include that miR-22 effectively inhibits tumor growth and metastasis by targeting and inhibiting ATP citrate lyase (ACLY), providing potential therapeutic benefits for osteosarcoma, prostate cancer, cervical cancer, and lung cancer." (PMID 39445018, 2024). "Aberrantly activated enzymes involved in the metabolism of FAs such as ATP citrate lyase (ACLY), fatty acid synthase (FASN), and acetyl-CoA carboxylase (ACC) in normal cells accelerated cancerous transformation in lung cancer." (PMID 39478862, 2024). "ARHGEF3 enhances ACLY protein stability by reducing acetylation at Lys17 and Lys86 of ACLY, leading to the dissociation of ACLY from its E3 ligase, NEDD4, making it a promising therapeutic target in non‐small cell lung cancer." (PMID 39778006, 2025). "ATP citrate lyase (ACLY), which is a key enzyme of de novo fatty acid synthesis, was found to be upregulated in numerous types of cancer, and it is inhibited by miR-22 in osteosarcoma and lung cancer cells." (PMID 34680164, 2021).
hepatocellular carcinoma (39 papers, 2020 to 2026). A malignant tumor that arises from hepatocytes. "Using metabolic dysfunction-associated steatohepatitis-driven hepatocellular carcinoma mouse models, an ATP citrate lyase inhibitor reduces tumour burden and enhances efficacy of current standards of care." (PMID 40739358, 2025). "Recently, it was shown that genetic ACLY deficiency or ACLY inhibition leads to increased immunogenicity and, consequently, inhibits the development/progression of hepatocellular carcinoma, supporting the notion that Tgr5 modulates cellfunction via metabolic-epigenetic pathways." (PMID 41377671, 2025). "Ubiquitin-specific protease 22 (USP22) stabilizes PPARγ due to deubiquitination, which increases acetyl-CoA carboxylase (ACC) and ATP citrate lyase (ACLY) expression and induces de novo lipogenesis as a risk factor for hepatocellular carcinoma (HCC)." (PMID 35954274, 2022). "The ATP citrate lyase (ACLY) serves as the initial rate-limiting enzyme in de novo lipogenesis, exhibiting high expression levels in both hepatocellular carcinoma (HCC) tissues and liver cancer stem cells (LTICs)." (PMID 40028341, 2025). "Overall, this research reveals that hypoxia-induced USP13 expression drives ferroptosis resistance and tumor immune evasion in hepatocellular carcinoma through the stabilization of ACLY." (PMID 41330897, 2025). "Since differences in ACLY splicing patterns is observed in tumors versus normal tissues, we re-expressed each isoform in an Acly KO mouse hepatocellular carcinoma cell line to better investigate cancer-specific phenotypes." (PMID 38815867, 2024). "We had also recently demonstrated that ACLY overexpression or activation drive hepatocellular carcinoma stemness and metastasis." (PMID 39399493, 2024). "The interaction between USP30 and ACLY leads to the deubiquitination of ACLY, resulting in the increased stability of ACLY, and thereby promoting adipogenesis, inflammation and tumorigenesis in hepatocellular carcinoma." (PMID 38426936, 2024). "Hepatocellular carcinoma samples were divided into low‐expression group and high‐expression group according to expression grade of ACLY." (PMID 33393219, 2021). "USP30 promotes stabilization of dynamin-related protein 1 (DRP1) or ATP citrate lyase (ACLY), resulting in accelerated development of hepatocellular carcinoma." (PMID 34381024, 2021). "Increased expression and activity of ACLY have been observed in various cancers including glioblastoma, colorectal cancer, BC, and hepatocellular carcinoma, suggesting that targeting ACLY may be an effective approach for anticancer therapy." (PMID 41421797, 2025). "However, USP13 and USP30 can mediate deubiquitination of ACLY, increasing the stability of ACLY to promote development of ovarian cancer and hepatocellular carcinoma, respectively." (PMID 33004065, 2020). "In addition, NAT10 can specifically upregulate the expression of the nucleic acid acetyl coenzyme A (acetyl-CoA) to drive chemoresistance in hepatocellular carcinoma through the acetylation of ATP citrate lyase (ACLY) at K468, and K468 is required for the nuclear localization of ACLY." (PMID 41316475, 2025). "A similar pro-invasive role for ACLY has been reported in hepatocellular carcinoma (HCC), in line with its function in sustaining metastatic traits." (PMID 41411367, 2025). "In addition, it has been found that increased ACC expression is accompanied by increased FASN and ACLY expression in prostate and hepatocellular carcinoma 39, indicating that ACC may play a synergistic role with FASN and ACLY to promote tumor growth." (PMID 37497413, 2023). "ACLY is overexpressed in patients with hepatocellular carcinoma (HCC), indicating shorter overall survival (OS), compared with low ACLY levels." (PMID 37041584, 2023).
hepatocellular carcinoma (continued). "Finally, as ACLY is also overexpressed in a wide variety of tumors, such as hepatocellular carcinoma, it is reasonable to suppose that liposomal HCA might be useful for the treatment of cancer, maybe in combination with other drugs." (PMID 33096779, 2020). "The results revealed that ACLY expression was broadly elevated in several cancers, including CCA, hepatocellular carcinoma, esophageal carcinoma, and head and neck squamous cell carcinoma." (PMID 39399493, 2024). "Bempedoic acid as an ATP citrate lyase inhibitor, which reduces low-density lipoprotein (LDL) cholesterol levels, has been demonstrated to inhibit hepatocellular carcinoma in mice." (PMID 37958642, 2023). "Overexpression of METTL14 in NAFLD models and hepatocellular carcinoma samples mediates m6A methylation of ACLY and SCD1, leading to upregulation of ACLY and SCD1 proteins, triglyceride and cholesterol production, and lipid droplet accumulation." (PMID 37420298, 2023). "This study aimed to evaluate the effects and mechanisms of ACLY and its inhibitor BMS‐303141 on hepatocellular carcinoma (HCC)." (PMID 33393219, 2021). "In addition, USP30 deubiquitinates and stabilizes ACLY and FASN and is overexpressed in the high-fat diet (HFD)-induced hepatocellular carcinoma (HCC)." (PMID 37176148, 2023). "In a mouse hepatoma model, metformin decreased de novo fatty acid synthesis by reducing, transcriptionally, the expression of acetyl CoA carboxylase, fatty acid synthase (FASN) and ATP citrate lyase (ACLY)." (PMID 33182253, 2020). "Further analyses of lipid-metabolism enzymes in sorafenib-resistant hepatoma cells showed that ACLY, ACC and FASN were activated to varying degrees, especially ACLY expression, which suggested that ACLY may play an important part in the sorafenib resistance of HCC15." (PMID 35154461, 2022). "In addition to activating SREBP1, MYC directly regulates the expression of key enzymes involved in FA synthesis, such as ACLY, ACC, FASN, and SCD1, which have been shown to drive tumorigenesis in hepatocellular carcinoma (HCC)." (PMID 37700339, 2023).
prostate carcinoma (38 papers, 2016 to 2025). A carcinoma that arises from epithelial cells of the prostate gland. "Inhibition of ACLY causes the growth suppression of the prostate cancer cell line." (PMID 29546056, 2018). "The authors further demonstrated that ACLY inhibition by siRNAs enhances the apoptosis of PC-3 and LNCaP prostate cancer cells induced by Cucurbitacin B and that Cucurbitacin B downregulates the expression of ACLY in PC-3 and LNCaP prostate cancer cells." (PMID 40214422, 2025). "Substantiating these findings, the tumor suppressor miR-22 was found to mediate its anticancer effect by inhibiting ACLY activity in PC-3 prostate cancer cells." (PMID 40214422, 2025). "Together, these findings indicate that ACLY contributes to the survival of breast and prostate cancers via cell death inhibition." (PMID 40214422, 2025). "Existing research indicates that ACLY is expressed highly in a wide range of cancers, including colorectal, liver, gastric, and prostate cancers, making ACLY a potentially effective therapeutic target for cancer by affecting lipid metabolism." (PMID 38755125, 2024). "For example, c-Myc maintains the glycolytic activity and increases the expression of key fatty acid synthesis genes, such as ATP citrate lyase, acetyl-CoA carboxylase alpha, and fatty acid synthase, thus promoting prostate cancer progression." (PMID 39253786, 2024). "For example, ectopic expression of MYC in prostate cancer leads to an increase in the expression of ACLY, ACC1, and FASN, resulting in promoted lipid accumulation." (PMID 37151387, 2023). "One of the interesting findings is that PKD3 promotes lipid synthesis by regulation of SREBP1 expression and nuclear entry as well as FASN and ACLY expression in prostate cancer cells." (PMID 31772672, 2019). "In prostate cancer, CuB significantly and specifically inhibited prostate cancer cell growth by inhibiting ATP citrate lyase (ACLY) phosphorylation." (PMID 31308852, 2019). "In this study, we demonstrated that PKD3 contributes to cell proliferation by modulation of SREBP1-mediated expression of FASN and ACLY as well as de novo lipogenesis in prostate cancer cells." (PMID 31772672, 2019). "Sp1 activation in colon and prostate cancers is associated with the activation of several genes involved in fatty acid synthesis, such as FAS, ATP citrate lyase (ACLY) and Acetyl-CoA carboxylase (ACACA)." (PMID 29865240, 2018). "The growth inhibitory effect of GS in prostate cancer has also been proposed to be due to inactivation of ATP citrate lyase (ACL or ACLY) which has been shown to exhibit crosstalk with the AKT signaling." (PMID 28261317, 2017). "In summary, our data points to the crucial role of ACLY-dependent fatty acid synthesis in coordinating endoplasmic reticulum and energetic homeostasis in prostate cancer cells." (PMID 27248322, 2016). "Consistent with a role for fatty acid metabolism in sustaining AR levels in prostate cancer in vivo, AR mRNA levels in human prostate tumors correlate positively with expression of ACLY and other fatty acid synthesis genes." (PMID 27248322, 2016). "Inhibiting lipogenic enzymes such as fatty acid synthase (FASN), acetyl-CoA carboxylase (ACC), or ACLY produces anti-cancer effects both in prostate cancer cell lines and mouse models." (PMID 27248322, 2016). "Moreover, it has been previously demonstrated in earlier studies that ACLY knockdown by siRNAs inhibits cell cycle progression and induces apoptosis of PC-3M prostate cancer cells." (PMID 40214422, 2025). "In addition, it was found that the promotion of apoptosis of human prostate cancer cells by CuB is related to ATP citrate lyase (ACLY) and can be offset by overexpression of ACLY." (PMID 40869325, 2025). "ACLY has been reported as a cell survival factor in both breast and prostate cancers." (PMID 40214422, 2025). "In addition, the ACLY levels in osteosarcoma, prostate cancer, cervical cancer and lung cancer cells were significantly higher than those in normal tissues." (PMID 39086974, 2022).